ERBB3 (erb-b2 receptor tyrosine kinase 3)
Diseases named in the same sentence as ERBB3 in open-access papers (continued):
Sharing a sentence is not in itself a finding about the gene and the disease.
cancer (continued). "The finding that ErbB3 regulates endocytic recycling of Integrin β1 in nonmalignant breast epithelial cells raises the question of whether this mechanism is also relevant in cancer cells overexpressing ErbB3." (PMID 41348103, 2026). "In addition, targeting ErbB3 in isolation may not be sufficient to fully inhibit cancer cell signaling." (PMID 39020378, 2024). "Therefore, dual inhibition of EGFR and ERBB3 may better prevent treatment-refractory cancer progression as opposed to solely targeting EGFR, especially in tumors overexpressing DARPP-32." (PMID 34675407, 2022). "Such cancers might be very sensitive to inhibition of ERBB2-ERBB3, and there are several recent reports of good responses in patients to anti-ERBB2 or anti-ERBB3 therapy, including anti-ERBB3 antibody and HER-family kinase inhibitors such as the pan-ERBB inhibitor afatinib." (PMID 33413557, 2021). "However, no ErbB3-targeted therapy has been approved for cancer treatment to date." (PMID 30961642, 2019). "We started our investigation by evaluating the correlation between ERBB3 abundance and the relapse-free survival (RFS), namely the time that the patient survives without any cancer sign after primary treatment." (PMID 35406375, 2022). "Other ERBB-family-receptors (ERBB2, ERBB3, and ERBB4) were barely expressed in basal cancers, whereas non-basal BLCA showed increased mRNA expression of different ERBBs." (PMID 32978523, 2020). "To show that EGFR ligands do not affect the phosphorylation of ErbB3, we investigated the phosphorylation of EGFR and ErbB3 in cancer cell lines treated with EGF, transforming growth factor-α (TGF-α), or heparin-binding EGF-like growth factor (HB-EGF)." (PMID 31615015, 2019). "This revealed three different cancer subsets based on i) enrichment of EPHB2+ cells and lack of ERBB3+ cells, ii) absence of EPHB2+ cells or iii) the presence of both ERBB3+ and EPHB2+ cancer cell populations." (PMID 26367378, 2015). "Furthermore, by examining the “inactive” pseudokinase ErbB3 and characterizing its weak activity, we justify an alternate means of resistance to ErbB TKI inhibition and propose that targeting of ErbB3 may represent a superior therapeutic strategy for certain ErbB-driven cancers." (PMID 21701703, 2011). "Historically, EGFR inhibitors have not been effective against KRAS-mutant cancers; however, second generation inhibitors have shown promise in treating both KRAS- and EGFR-mutant tumors by targeting all members of the ErbB family of proteins (EGFR/ERbB1, HER2/ErbB2, HER3/ErbB3, HER4/ErbB4)." (PMID 36674513, 2023).
adenocarcinoma (28 papers, 2009 to 2026). A common cancer characterized by the presence of malignant glandular cells. "Notably, high expression of either ERBB2 or ERBB3 is associated with resistance of adenocarcinoma to chemotherapy, although these data should be interpreted with caution due to the low sample sizes available." (PMID 31032816, 2019). "The present study also revealed that ERBB3 was highly expressed in HPV-infected cell lines and was associated with adenocarcinoma." (PMID 36911370, 2023). "The median level of ERBB3 expression in adenocarcinomas (0.141) was significantly higher than that in normal tissues (0.079) (Wilcoxon matched-pairs test, p<0.0005)." (PMID 26367378, 2015). "This pattern was also observed in adenocarcinomas where ERBB3 and EPHB2 marked distinct cell populations (n = 10)." (PMID 26367378, 2015). "While no data on EGFR mutations were available in the present series, over-expression of ERBB3 was more common in females with adenocarcinoma, supporting, thus, results of the Japanese study." (PMID 22848476, 2012). "It is possible that selection for CD49+/EpCAM+ cells in combination with culture conditions to increase ErbB3 expression over EGFR expression may increase the likelihood of generating luminal adenocarcinomas." (PMID 26228788, 2015). "Multiparous transgenic female mice expressing NRG1, a ligand for ERBB3 and ERBB4, under control of the MMTV promoter also develop adenocarcinomas in the mammary glands at a median age of 12 months, suggesting ErbB4 to be contributing to neuregulin-induced carcinogenesis." (PMID 25516216, 2014).
breast (9 papers, 2011 to 2025). "A time-course mRNA expression analysis of the NRG1 isoforms, ErbB3 and ErbB4 receptors, and their co-receptors ErbB2 and ErbB1, was performed on SDF muscle after median nerve injury." (PMID 29568012, 2018).
infection (8 papers, 2010 to 2022). The state of being infected such as from the introduction of a foreign agent such as serum, vaccine, antigenic substance or organism. "Irrespective of the precise immunological mechanisms, our study suggests that ERBB3 may be an important molecular link between genetic susceptibility, infection and the adaptive immune response, which are all believed to contribute to T1D pathogenesis." (PMID 20668683, 2010). "Regardless, the EGFR–ErbB3 heterodimerization we observed was essential for the infection-induced EGFR activation as well as for bacterial invasion of the hBMECs because the ErbB3 knock-down significantly delayed and attenuated these phenotypes." (PMID 30687645, 2018). "During our studies of ERBB3 surface expression, we observed individual variation in surface ERBB3 after in vitro treatment with infection mimics." (PMID 20668683, 2010). "A subset of DC (CD11c+CD14− cells) also expresses ERBB3 after treatment with the three infection mimics." (PMID 20668683, 2010). "Surface ERBB3 was almost undetectable in fresh PBMCs; however, surface ERBB3 protein was dramatically increased after cultures with three different infection mimics (LPS, polyI:C and CpG)." (PMID 20668683, 2010). "We first checked the transcription of these ErbB members by real-time PCR and found that the transcription levels of EGFR, ErbB2, and ErbB4 did not significantly change in response to SC19 infection, while ErbB3 showed a significant decrease since 2 h post infection." (PMID 27756321, 2016). "We further demonstrated that the time-dependent phosphorylation of EGFR in response to SC19 infection became attenuated in sh-ErbB3 transfected cells, and vice versa, 5 μM AG1478 treatment significantly blocked the infection-induced phosphorylation of ErbB3, compared with the vehicle control." (PMID 27756321, 2016). "This evidence confirmed our hypothesis that SS2 infection of hBMEC induced the formation of EGFR/ErbB3 heterodimers." (PMID 27756321, 2016). "We have demonstrated that ERBB3 is expressed on the surface of CD11c+ cells (monocytes and DC) upon in vitro stimulation by infection mimics, suggesting that ERBB3 may play an important role in innate immune response." (PMID 20668683, 2010). "Flow cytometry results show that siRNA silencing the expression of SGK3, ULK3, ERBB4, STK17B can reduce the infection efficiency of ORFV-GFP virus, while siRNA silencing the expression of MST1R, PAK4, ERBB3 can increase the infection of ORFV-GFP virus efficient." (PMID 35401439, 2022). "By using genotype 1b replicon cells as well as an infection-based system we found that while transcript and protein levels of EGFR and ErbB2 were up-regulated or unaffected, respectively, HCV induced a substantial reduction of ErbB3 and ErbB4 expression." (PMID 26886748, 2016). "We similarly observed the inverse result after immunoprecipitation with an anti-ErbB3 antibody, showing that EGFR binding was increased upon the phosphorylation of ErbB3, which further strengthened our hypothesis on the formation of EGFR/ErbB3 heterodimers in response to SS2 infection." (PMID 27756321, 2016).
colon polyp (3 papers, 2021 to 2022). "Although endogenous ERBB3 deletions have not been widely explored, it has been observed in knockout mouse models that the deletion of HER3 led to the reduction in proliferation of colon polyps." (PMID 36551663, 2022). "Whereas 66% of the ApcMin/+ control mice developed at least one colon polyp, all ApcMin/+ lacking ERBB3 developed at least two colon polyps." (PMID 34843459, 2021). "Although ErbB3 is expressed widely, this family has not manifested other malignancies (the proband has had non-cancerous colonic polyps)." (PMID 34274969, 2021). "Similar to the C57BL/6J-ApcMin/+ model, a significant increase in AOM-induced colon polyp multiplicity was observed in the absence of ERBB3 on the C57BL/6J background." (PMID 34843459, 2021).
cardiovascular diseases (2 papers, 2021). "To date, ERBB3 has been widely used as a tumour marker; however, it was recently reported to be associated with cardiovascular diseases." (PMID 34176482, 2021). "In addition, ERBB3 has been reported to play an important role in the maintenance and development of cardiovascular disorders." (PMID 34176482, 2021). "Several studies have reported the involvement of ErbB3 in cardiovascular diseases." (PMID 33988127, 2021). "ERBB3( also known as HER3) plays a considerable role in the development of cardiovascular diseases." (PMID 34176482, 2021).
digestive tumor (2 papers, 2017 to 2022). "We have recently observed that GI tumor cells treated with the clinically relevant drug combination of [neratinib + valproate] (NCT03919292) also cause surviving cells to evolve with higher ERBB3 signaling." (PMID 35035775, 2022).
hematologic tumors (1 paper, 2021). "The expression levels of ErbB2 and ErbB3 decreased in hematologic tumors compared with it in solid tumors." (PMID 34658878, 2021). "By detecting the expression of kinases at the gene level in the PI3K/HDAC pathways with the CCLE database, we found that the expression levels of ErbB2 and ErbB3 in hematologic tumor cells were lower than those in solid tumors." (PMID 34658878, 2021). "Thus, the low expression of ErbB2 and ErbB3 stabilized the PI3K/Akt signaling pathway in hematologic tumors, thereby enabling compound 23 to exhibit more potent antitumor efficacy than against solid tumor cells." (PMID 34658878, 2021). "Therefore, we suggest that the efficacy of compound 23 against hematologic tumors may be related to the expression levels of ErbB2 and ErbB3 in hematologic tumor cells." (PMID 34658878, 2021).
neurodegenerative disease (1 paper, 2018). A disorder of the central nervous system characterized by gradual and progressive loss of neural tissue and neurologic function. "The reduced expression of ERBB3 gene could contribute to insufficient remyelination associated with the expansion of neurodegenerative diseases like MS and Alzheimer's." (PMID 29503661, 2018).
ERBB3 also shares sentences with these, for which no sentence is quoted: ovarian tumor (7 papers); esophageal cancer (5); ampullary cancer (4); cholangiocarcinoma (4); Hyperglycemia (4); lymphoma (4); multiple myeloma (4); rectal cancer (4); type 2 diabetes mellitus (4); Barrett esophagus (3); biliary tract cancer (3); cervical tumors (3); colon adenocarcinoma (3); colorectal adenocarcinoma (3); leukemia (3); metastasis (3); oral squamous cell carcinoma (3); acral melanoma (2); adenocarcinoma of the uterine cervix (2); age-related hearing impairment (2); astrocytoma (2); brain cancer (2); cardiac hypertrophy (2); CNS tumors (2); epilepsy (2); fibrosarcoma (2); gastrointestinal disease (2); granulosa cell tumor (2); gynecological cancers (2); hypopharyngeal carcinoma (2).
A further 142 diseases each share a sentence with ERBB3 in 2 papers or fewer.